FAM90A13 (family with sequence similarity 90 member A13)
Synonyms: FAM90A13P
Tractability: No criterion of Open Targets' tractability assessment is met for any kind of drug.
Gene: Protein-coding gene on chromosome 8 (7,279,770 to 7,282,780, forward strand). Ensembl gene ENSG00000223885.
Subcellular location (Human Protein Atlas): Nucleoplasm; Nucleoli
Homologues: Orthologues: mouse Fam90a1b (28% identical), mouse Fam90a1a (27% identical), rat Fam90a1l1 (26% identical). Paralogues in human: FAM90A15 (99% identical), FAM90A14 (99% identical), FAM90A5 (99% identical), FAM90A23 (99% identical), FAM90A24 (99% identical), FAM90A3 (98% identical), FAM90A11 (98% identical), FAM90A16 (98% identical), FAM90A17 (98% identical), FAM90A12 (98% identical), FAM90A8 (98% identical), FAM90A9 (98% identical), and 9 more.